KRT18 (keratin 18)
Description:
Structural component of intermediate filaments in simple epithelial cells. Forms obligate heteropolymers with a type II keratin KRT8, mechanical stability and resilience to epithelial cells. KRT8/KRT18 filaments are involved in ARHGEF40-mediated actin stress fiber formation and tensional force-induced stress fiber formation and reinforcement. Organization and orientation of KRT8/KRT18 filaments are responsible for the properly elongated morphology of epithelial tubules (By similarity). Also acts downstream of ROCK kinase activation as part of a positive feedback mechanism in response to cellular mechanical stress loading. Involved in the uptake of thrombin-antithrombin complexes by hepatic cells (By similarity). When phosphorylated, plays a role in filament reorganization. Involved in the delivery of mutated CFTR to the plasma membrane. Involved in interleukin-6 (IL-6)- mediated barrier protection.
Synonyms: CK-18; K18; CYK18
Tractability: PROTAC: UniProt records ubiquitination sites on it; ubiquitination databases record sites on it; its protein half-life has been measured.
Gene: Protein-coding gene on chromosome 12 (52,945,688 to 52,952,911, forward strand). Ensembl gene ENSG00000111057.
Subcellular location: Nucleus matrix; Cytoplasm, perinuclear region; Nucleus, nucleolus; Cytoplasm
Subcellular location (Human Protein Atlas): Cytosol
Pathways (Reactome):
Developmental Biology: Developmental Lineage of Mammary Gland Alveolar Cells; Developmental Lineage of Mammary Gland Luminal Epithelial Cells; Formation of the cornified envelope; Keratinization
Gene Ontology:
Molecular function: cadherin binding involved in cell-cell adhesion; protein binding; RNA binding; scaffold protein binding; structural constituent of muscle; structural molecule activity
Biological process: Golgi to plasma membrane protein transport; intermediate filament cytoskeleton organization; negative regulation of apoptotic process; anatomical structure morphogenesis; intermediate filament organization; cell-cell adhesion
Cellular component: adherens junction; centriolar satellite; cytoplasm; cytosol; extracellular exosome; intermediate filament; keratin filament; microtubule organizing center; cytoskeleton; nuclear matrix; cell periphery; nucleolus; perinuclear region of cytoplasm; protein-containing complex
Genetic constraint (gnomAD): Loss-of-function variants: 7 observed, 32.03 expected, observed/expected ratio (o/e) 0.22, 90% interval 0.12 to 0.41. The upper end of that interval is the gene's LOEUF score, 0.41, which puts it in group 1 of 6, group 1 being the genes least tolerant of losing a copy. Missense variants: 392 observed, 536.03 expected, observed/expected ratio (o/e) 0.73, 90% interval 0.67 to 0.8. Synonymous variants: 193 observed, 218.03 expected, observed/expected ratio (o/e) 0.89, 90% interval 0.79 to 1.
Homologues: Orthologues: chimpanzee KRT18 (100% identical), macaque KRT18 (99% identical), dog KRT18 (89% identical), mouse Krt18 (87% identical), guinea pig Krt18 (87% identical), pig KRT18 (87% identical), rat Krt18l1 (85% identical), rat Krt18 (71% identical), tropical clawed frog krt18 (60% identical). Paralogues in human: KRT14 (48% identical), KRT15 (46% identical), KRT16 (46% identical), KRT24 (46% identical), KRT10 (44% identical), KRT17 (44% identical), KRT12 (43% identical), KRT36 (43% identical), KRT19 (42% identical), KRT27 (42% identical), KRT13 (41% identical), KRT20 (41% identical), and 56 more.
Diseases named in the same sentence as KRT18 in open-access papers:
KRT18 is named in the same sentence as 321 diseases in open-access papers, as found by Europe PMC text mining. Sharing a sentence is not in itself a finding about the gene and the disease. The quoted sentences say what the papers report.
breast carcinoma (135 papers, 2006 to 2026). "Keratin 18 plays biological functions in carcinogenesis, and its expression may serve as a differential diagnostic marker in various cancers such as small cell lung cancer and breast cancer." (PMID 32408199, 2020). "Differentially expressed genes (DEGs) such as KRT8 and KRT18, associated with epithelial function, were highly expressed in these domains, while NUPR1, a prognostic marker in early-stage breast cancer, was upregulated." (PMID 40838787, 2025). "We suggest that keratin 18 and protocadherin 17 should be further investigated in bitches because of their role in women’s breast cancer." (PMID 39057100, 2024). "It is important to emphasize that the keratin 18 and protocadherin 17 proteins and their coding genes play an important role in the suppression of proliferation and tumor growth in breast cancer in women." (PMID 39057100, 2024). "For instance, KRT18 induces an epithelial–mesenchymal transition (EMT) in human breast cancer and KRT19 plays a critical role in breast cancer proliferation." (PMID 36672349, 2023). "For instance, the expression patterns of conventional tumor markers, such as the proliferating cell nuclear antigen (PCNA) and the minichromosome maintenance protein 3 (MCM3) in breast cancer were found to be similar to those of KRT18." (PMID 36949761, 2023). "A study has shown that Cytokeratin 18 has a certain correlation with tumor progression in neoadjuvant chemotherapy for breast cancer." (PMID 35434132, 2022). "In breast cancer, KRT18 was reported to critically contribute to initiation of transforming growth factor β1 (TGF-β1)–induced epithelial–mesenchymal transition (EMT) in breast epithelial cells." (PMID 34290732, 2021). "Our findings showed statistically insignificant changes in the level of Caspase-cleaved- (M30) and uncleaved- (M65) cytokeratin 18 fragments (apoptotic and necrotic indicators, respectively) during neoadjuvant chemotherapy in patients with breast cancer." (PMID 32215027, 2020). "Several other studies have shown that KRT18 plays an important role in gastric cancer, colorectal cancer, prostate cancer, and breast cancer." (PMID 32509787, 2020). "The present study aimed to investigate the relationship between baseline level and serum changes of cytokeratin 18 fragments M30 and M65 before and after neoadjuvant chemotherapy with pathologic response in breast cancer treatment." (PMID 32215027, 2020). "This study found statistically insignificant changes in serum M30 and M65 levels (cleaved and uncleaved fragments of cytokeratin 18) following neoadjuvant chemotherapy in breast cancer patients." (PMID 32215027, 2020). "Expression of the epithelial gene KRT18 was positive from as few as 50 spiked cells from the breast cancer cell lines SUM190 (basal) and MCF-7 (luminal)." (PMID 33095819, 2020). "Conversely, KRT18 was reported to suppress tumor aggressiveness and paclitaxel-resistance in paclitaxel-resistant prostate and breast cancers." (PMID 33330500, 2020). "In order to explore role of keratin 18 gene in breast cancer brain metastasis and hypomethylating agent treatment, we first measured the expression of the keratin 18 DNA, mRNA, and protein." (PMID 32408199, 2020). "Since lungs are a primary metastatic organ for breast cancer, lung samples from each mouse were stained for cytokeratin 18 (CK18) to detect metastasized tumor cells." (PMID 29330447, 2018). "Keratin 18 is an intermediate filament protein and can be used for detection of proliferating fractions in the breast cancer." (PMID 28704482, 2017). "The mean transcript expression of CDH1 and KRT18 were lower in the basal B breast cancer cells with low FRK transcript levels as compared to Basal A and Luminal cells that harbor high FRK transcript levels (P<0.05)." (PMID 29348886, 2017).
breast carcinoma (continued). "Consistently, flubendazole reduced mesenchymal markers (β-catenin, N-cadherin and Vimentin) expression and induced epithelial and differentiation marker (Keratin 18) expression in breast cancer cells." (PMID 25811972, 2015). "Flubendazole treated MDA-MB-231 cells exhibited the downregulation of Vimentin and upregulation of Keratin 18, indicating that flubendazole induced differentiation of breast cancer cells." (PMID 25811972, 2015). "Both the CRCTU and ATCC Walker 256 cell populations stained positively for cytokeratin 18, a marker of breast cancer cells." (PMID 23374226, 2013). "MDA-MB-231 human breast cancer cells have previously been found to express mixed staining patterns of human keratin 18 (luminal cell marker) and human keratin 14 (myoepithelial cell marker)." (PMID 23155468, 2012). "STAT1-/- ERα+ mammary tumors also showed elevated transcription of genes characteristic of luminal breast cancers (for example, keratin 8, keratin 18, XBP1, GATA3, MYB, AREG, and FOXA1)." (PMID 22264274, 2012). "Particularly, in breast carcinoma cells with high cytokeratin-18 and E-cadherin expression, i.e. epithelial phenotype, EpCAM displays growth- and invasion-promoting effects." (PMID 23110550, 2012). "Co-expression of VIM and cytokeratins (CKs) is associated with a more aggressive and metastatic phenotype in breast cancer; however our data demonstrates increased expression of VIM with an associated decrease in cytokeratin 18 levels in Clone #3." (PMID 19216797, 2009). "The four different ESR1 probes on the array defined two primary ESR1-associated probe set clusters, including genes (for example, GATA3, KRT8, KRT18) commonly used to define luminal-type breast cancers." (PMID 17850661, 2007). "Furthermore, tKRT81 was discovered to physically interact with and disrupt the filamentous organization of KRT18 in breast cancer cells." (PMID 37949677, 2024). "In the present study, KRT18 was over-expressed in breast invasive carcinoma (BRCA), further supporting that KRT18 could represent a candidate biomarker in breast cancer for predicting poor prognosis in breast cancer." (PMID 36949761, 2023). "FRK transcript levels were positively correlated with the transcript levels of E-cadherin and Cytokeratin 18 as well as in the breast cancer tissues mined from TCGA database where FRK correlated positively with E-cadherin in both normal and breast tumor tissue samples." (PMID 29348886, 2017). "Both ATRA and IIF down-regulated genes that supported the tumour stem cell phenotype maintenance (Slug, Notch-3 and Jagged-1) by blocking the NF-κB axis: these events were associated with re-expression of differentiation markers such as ERα and keratin-18 in breast carcinoma stem cells." (PMID 28465354, 2017). "The mammary tumors that arise in this model have characteristics of human luminal breast cancer including expression of cytokeratin 8, cytokeratin 18 and E-cadherin however, these tumors cluster most closely with human basal-like breast cancer when gene expression profiles are used." (PMID 27282619, 2016). "Moreover, it has been suggested that caspase-cleaved KRT18, a serum apoptosis product, could be a functional biomarker for predicting the response of breast carcinomas to chemotherapy." (PMID 36949761, 2023). "We propose that DNA hypermethylation of the keratin 18 gene may serve as a biomarker for diagnosis of brain metastasis of breast cancer or can be used to evaluate whether breast cancer patients with brain metastasis are potential candidates and would benefit from hypomethylating agent treatment." (PMID 32408199, 2020). "Moreover, the hypermethylated keratin 18 gene may be a potential drug target that can be used for the development of novel targeted therapy drugs in treating patients with brain metastasis breast cancer." (PMID 32408199, 2020).
breast carcinoma (continued). "A total of 44 human breast cancer cell lines and three immortalized breast epithelial lines were categorized as representing luminal or basal breast cancer subtypes based on the relative gene expression of cytokeratin 8/cytokeratin 18 and cytokeratin 5/cytokeratin 17, respectively." (PMID 19874578, 2009). "Expression of Pik3ca-mutations in luminal cells (e.g., using promoters MMTV, WAP and Krt8) mostly evoked adenosquamous mammary carcinomas, which exhibited mixed-lineage features highlighted by the presence of KRT14/KRT8 & KRT18 double-positive cancer cells." (PMID 40676433, 2025). "EPCAM and KRT18 were employed to label epithelial cells, whereas ALDH2, CD55, and ALDH6A1 were used to identify breast cancer stem cells." (PMID 40092692, 2025). "For basal-like breast cancer, it has been reported that these tumors are more heterogenous and can express luminal markers such as KRT7, KRT18 or vitamin D receptor." (PMID 40676433, 2025). "The top five hub genes for the hormone-like community were KRT18, JUP, KRT8, SH2D3A and PDLIM1; KRT18 and KRT8 are luminal markers in breast cancer while JUP (plakoglobin), SH2D3A and PDLIM1 are relatively undescribed in the context of cancer." (PMID 39556603, 2024). "Several known proteins (including HSP90AB1, HSPB1, LDHA, ENO1, PGK1, KRT18, and AKR1C2) and pathways were observed between model breast cancer cell lines related to hormone response, cell metabolism, and cell morphology." (PMID 36937585, 2023). "The plakoglobin (JUP), KRT8, KRT18, KRT19, CLDN4, and EPCAM, which their role in breast cancer metastasis was demonstrated in previous studies, are EMT markers." (PMID 34801010, 2021). "Lastly, we observed a decreased expression of keratin 18 (an epithelial maker) in 231Br cells due to hypermethylation, elucidating a potential mechanism of action of AZA in treating brain metastases from breast cancer." (PMID 32408199, 2020). "Another antibody array study revealed that cyclin D2, cytokeratin 18, cyclin B1, hnRNP m3-m4 and the monophosphorylated ERK were decreased in a doxorubicin resistant breast cancer cell line in comparison to a sensitive one." (PMID 31014274, 2019). "Analysis of breast cancer clinical datasets showed correlation (direct or inverse) of KRT expression with KLK6 including an inverse correlation of KLK6 and KRT18." (PMID 30980596, 2019). "In MCF-7 breast cancer cells, HCG induced expression of differentiation markers β-casein, cytokeratin-18 and E-cadherin, also supporting an antitumoral role of this hormone." (PMID 28754015, 2017). "Four genes from breast cancer stage III network pattern (KRT8, KRT17, KRT18 and HOXC10) physically interact with EGFR, a target gene of Lapatinib Breast cancer drug which is quite similar (greater than 50%) to Paroxetine (repurposed drug from LINCS)." (PMID 26892392, 2016). "We used primers for the gene sequences of UBB, ESR1 (for luminal or ER/PR+ cancer cells), HER2 and GRB7 (for HER2+ cancer cells), EPCAM, KRT7, KRT8, KRT18, and KRT19, all of which have been commonly discussed for the purpose of breast cancer diagnosis." (PMID 28936247, 2015). "As expected, this list contains numerous markers of breast cancer cells whose expression specificity was previously reported by other (notably ERBB3, XBP1, KRT18, IL6ST, CREB1, TFF1, TFF3)." (PMID 19104654, 2008). "KRT5/KRT18, for example, are dysregulated in cancers originating from basal epithelial cells, playing a role in epithelial-mesenchymal transition (EMT) in basal-like cancers such as breast cancer." (PMID 40722520, 2025). "Each of these was supported by (i) the upregulation of KRT18, KRT19, E-cadherin, and downregulation of vimentin in breast carcinoma; (ii) increased levels of GFAP, MAP2, and PSD-95 in astrocytoma; and (iii) increased NeuN, GAP-43, and NF200 levels in neuroblastoma." (PMID 39859209, 2025).
breast carcinoma (continued). "Notably, all the cancer cells from the four models showed high Krt18 expression, and only some cells from the BRCA1 model, a basal-like breast cancer model, showed a detectable Krt5 transcript." (PMID 34497807, 2021). "Keratin 18 is considered as a differentiation and epithelial marker, indicating differentiation and mesenchymal-epithelial transition (MET) of breast cancer cells, while Vimentin functions as a dedifferentiation and mesenchymal marker in breast cancer cells." (PMID 25811972, 2015). "Indeed, Aldh1 and cytokeratin 18 were expressed in a mutually exclusive way in both LCIS and ILC, consistent with Aldh1 marking undifferentiated breast cancer stem cells." (PMID 19583841, 2009). "For genes related to breast cancer estrogen signaling, GSEA analysis showed a progressive down-regulation of keratin 18 and NME1 from luminal A to basal tumors, which also correlated with ER(+)ve MDA-MB-435 cells; low expression of these genes correlates to poor prognosis and metastasis." (PMID 17883861, 2007). "Cytokeratin 18 levels, measured with the TPS test, also correlate to prostate cancer tumour load, and pretreatment CK18-Asp396 levels correlate to tumour load in breast cancer patients." (PMID 16685278, 2006). "Finally, novel metastatic biomarkers of KRT18 and KRT19 were detected in breast cancer CTCs." (PMID 34801010, 2021). "Microarray analysis of breast cancer cells with ZMYND8 knockout by siRNA revealed that depletion of ZMYND8 reduces the expression of terminal differentiation markers, such as epithelial cell adhesion molecule (EPCAM) and cytokeratin 18 (CK18), by 80% and 86%, respectively." (PMID 33670804, 2021). "We found that TF expression in breast cancer lines and tumors closely clustered with higher levels of EMT (high vimentin/low E-cadherin) and classical basal-type biomarkers KRT5, KRT14 and caveolin-1, while it clustered with lower levels luminal-type biomarkers KRT8, KRT18, ERBB3 and ESR1." (PMID 28938620, 2017). "The significant loss of cytokeratin 18 (KRT18), a well described luminal breast cancer marker, is worth mentioning, as the sole knockdown of KRT18 has been recently shown to induce EMT and stemness features in non-metastatic MCF-7 breast cancer cells." (PMID 36998085, 2023). "We also showed that vimentin, cytokeratin 18 (CK18), β-actin, and keratin 7 appeared to show increased O-GlcNAcylation in breast cancer tissues, but their glycosylation sites were not yet mapped." (PMID 25426101, 2014). "Godfroid et. al. further demonstrated the presence of cytokeratins KRT8, KRT18, and KRT19 on the outer surface of established human mammary carcinoma cells but not normal mammary cells." (PMID 20543960, 2010). "The protein expression levels of the two immune checkpoint molecules, CD200R and CD274, were measured as mean fluorescence intensity (MFI) in non-hematopoietic cells, identified by the expression of cytokeratin 18 and CD326 (EpCAM) and dim/negative expression of CD45, from breast cancer biopsies." (PMID 39858472, 2025). "Interestingly, comparative analysis of the basal‐like vs. luminal breast cancer cell types markers in ABI1 KO mice showed that the genes of basal‐like cells (Krt14, Vim) are responded to Abi1 depletion, however luminal cell type genes markers (Krt8, Krt18, Sox9, Estr1) do not." (PMID 34967509, 2022).